IL6 (interleukin 6)
Diseases named in the same sentence as IL6 in open-access papers (continued):
Sharing a sentence is not in itself a finding about the gene and the disease.
influenza (continued). "Moreover, previous studies found a positive correlation between plasma IL-6 levels and severity of symptoms, as well as exacerbation of disease and lung damage in influenza infected patients." (PMID 26859566, 2016). "Our findings suggest that IL-6 secretion from LPS-stimulated PBMCs was associated with the incidence of cold or flu episodes, but was not related to the severity of cold or flu symptoms captured via self-reported URTI questionnaire." (PMID 25788896, 2015). "We also found that IL-6 secretion from LPS-stimulated PBMCs was associated with self-reported incidence of cold or flu episodes, and IFN-γ secretion from T cells was associated with self-reported severity of cold or flu symptoms in the past month." (PMID 25788896, 2015). "From these two approaches, we found that IL-6 secretion was higher in participants with self-reported cold or flu episodes compared to participants without cold or flu episodes, and was significantly associated with cold or flu incidence in the past month." (PMID 25788896, 2015). "Syncytin-1 exposure leads to a marked reduction in pDC release of IFN-α/λ to influenza, but it also stimulates enhanced release of IL-10 with the potential to further impair adaptive responses as well as enhanced release of IL-6 and IL-1β both of which potentially will worsen systemic inflammation." (PMID 25831059, 2015). "IL-6 is involved in the development of influenza-specific memory CD4 T cells." (PMID 26282854, 2015). "As expression of IL-6 and TNFα were induced in our mouse model upon influenza infection, we hypothesized that IL-1β drove the observed inflammation by altering their production." (PMID 24918427, 2014). "The peak expression of IL-6 and TNFα upon influenza infection was reached faster in C57BL/6 wild type mice at day 1 post infection as compared to day 3 in BALB/c mice, and thus coincided with the earlier response in pulmonary resistance observed in the C57BL/6 strain." (PMID 24918427, 2014). "IL-6, except for its role in resolution of innate immunity, is also an important cytokine to regulate the shift from innate immune response to adaptive immune response and enhance the proliferation of T cells and influenza-specific T memory cells." (PMID 24465940, 2014). "The suite of cytokines and chemokines assessed here, namely, TNF-α, IL-6, CCL2, CCL3, CXCL2 and IL-1β, are known to promote the inflammation caused by influenza at early stages of the infection phase, i.e. during the cytokine storm, and have been shown to underpin the pathology and morbidity." (PMID 23577160, 2013). "IL-6 has been reported along with IL-12p70 as markers of critical pandemic influenza illness." (PMID 21880131, 2011). "For pH1N1 influenza, high plasma IL-6 concentration at presentation (adjusted OR 12.6, 95%CI 2.6–61.5, per log10 unit increase; P = 0.002) was independently associated with ICU admission, adjusted for age, comorbidity and time interval from onset-to-presentation." (PMID 22022504, 2011). "IL-6 and IFN-γ are associated with antiviral immune responses during influenza infection." (PMID 21749768, 2011). "Experiments have shown that only the peak values of IFN-α and IL-6 could respectively be detected within 24 and 30 h in the serum of infected animals, as well as in the plasma of pediatric patients with severe influenza." (PMID 21569236, 2011). "To confirm that virus-specific Treg activity was more readily detectable in the absence of IL6, we stimulated co-cultures of CD4+CD25− cells (obtained from influenza-infected WT mice) and CD4+CD25+ cells purified from either influenza-infected WT or IL-6−/− mice with APCs infected with the virus." (PMID 18389078, 2008). "Additionally, after influenza vaccination, increases in IL-6 and TNF-α are observed." (PMID 40718526, 2025). "IL‐6 inhibitors have been shown to be protective in patients with COVID‐19 and it has been proposed that IL‐6 inhibitors may also be protective during severe influenza infection." (PMID 40420617, 2025).
influenza (continued). "Additionally, IL-6 has been suggested to facilitate lung repair during influenza infection." (PMID 40692679, 2025). "While the antiviral protective mechanism of IRF7 in the immune response is well defined, there is evidence suggesting that MX1 may exert its anti-influenza protective effect by downregulating factors such as IL-6, IL-1β and TNFα, among others, involved in excessive cytokine response." (PMID 38932312, 2024). "Additionally, IL-6 can protect neutrophils from influenza-induced cell death; thus, the contemporaneous significant reduction of local levels of this cytokine may have influenced neutrophil abundance within the airways." (PMID 38060822, 2024). "Moreover, stimulation with the influenza vaccine or CpG resulted in increased IL-6 levels in the culture supernatants, suggesting innate cell activation as well as IFNγ and TNF which may indicate Th1 helper responses." (PMID 39355250, 2024). "Furthermore, by analyzing the relationship between SEPT2 and proinflammatory cytokines, we discovered that SEPT2 was negatively correlated with IL-6 and IL-12 p40 in influenza patients, which confirmed our finding that SEPT2 is involved in the negative regulation of inflammation." (PMID 37978190, 2023). "Thus, the TLR4, CD14, MyD88, and NF-κB p65 in TLR4/NF-κB p65 signaling pathway, HIF1 α, VEGF, IL17A, and IL6 in HIF-1α/IL17 signaling pathway may be the targets responsible for the anti-inflammatory function of HSSD in treating influenza." (PMID 36386710, 2022). "Furthermore, during influenza infection, the host produces the pro-inflammatory IL-6 and IL-1." (PMID 35328462, 2022). "Moreover, experimental studies investigating influenza found an enhancement of mortality in IL-6 knockout mice because of a reduction in macrophage infiltration in the lung and epithelial cell survival, increased fibroblast proliferation, and collagen deposition." (PMID 36685603, 2022). "Interestingly, infection of macaques with 1918 H1N1 was found to greatly increase IL-6 levels compared to macaques infected with conventional H1N1, suggesting IL-6 may also play an important role in the pathogenesis of severe influenza." (PMID 33499234, 2021). "Thus, the role of IL-6 for diagnosing the progression of influenza warrants special attention." (PMID 34692664, 2021). "However, IL-6 appears to have dual roles depending on whether it is an acute or chronic situation, as IL-6 was crucial for lung repair in an influenza-induced lung injury model through reducing fibroblast accumulation and promoting epithelial cell survival." (PMID 33419174, 2021). "Using influenza as a model, live attenuated and killed inactivated influenza vaccines stimulate many shared pathways such as signaling of many interleukins (including IL-1, IL-4, IL-6, IL-13, IL-20, and IL-27), interferon signaling, MARK1 activation, and neutrophil degranulation." (PMID 33777032, 2021). "Moreover, splenic unstimulated B cells from P2KO mice make higher levels of TNF-α and IL-6 mRNA than those from WT mice and these negatively correlate with B cell function, measured in vivo by the response to the influenza vaccine and in vitro by AID mRNA expression in stimulated B cell cultures." (PMID 32180773, 2020). "However, the specific importance of IL-6 in infant immunity to influenza is less clear." (PMID 33193346, 2020). "Furthermore, we have shown that the combined effects of IL-2 and IL-6 as a supplement in ex vivo influenza-challenged PBMC restores the CD8 T cell response to that seen in younger adults; the problem is that older adults have a lower frequency of CD8 T cells at baseline." (PMID 32399058, 2020). "This study suggests that IL-6 may be exploited for lung repair during influenza infection." (PMID 28262742, 2017).
influenza (continued). "Importantly, although the young adults have higher frequencies of M1 tetramer+ cells, there is approximately a 4 to 5-fold increase in the frequency of these cells in both young and older adults in response to influenza challenge with the addition of IL-2 plus IL-6 to the cultures." (PMID 27322555, 2016). "Thus these results suggest that in older individuals, the population of influenza-specific memory T cells generated by vaccination, or re-called from earlier exposures, are defective, and that the combination of IL-2 and IL-6 is able to act together to substantially enhance responses." (PMID 27322555, 2016). "Infection with highly pathogenic influenza such as H5N1 and H7N9 induces extensive infiltration of macrophages and neutrophils, upregulation of pro-inflammatory cytokines such as TNF-α, IL-1β, IL-6, IL-8 and IP-10, and cell death resulting in severe pulmonary inflammation." (PMID 27315117, 2016). "Therefore, suppressed induction of IL-6 expression after infection with influenza could have an impact on T cell–dependent adaptive immune responses, although we did not measure T-cell responses in the present study." (PMID 20920950, 2011). "Thus, influenza-infected DCs may represent at least one relevant source of IL-6 in the system under study here." (PMID 18389078, 2008). "In the random forest model, the clinical features' importance in the Influenza group, from highest to lowest, are as follows: PCT, Neutrophil Proportion, IL6, etc.." (PMID 40158620, 2026). "Elevated levels of pro-inflammatory cytokines, especially IL-6 and tumor necrosis factor-alpha (TNF-α), are consistently observed in severe cases of influenza." (PMID 41583233, 2025). "Mice vaccinated with BPZE1 as infants showed reduced production of the four pro-inflammatory cytokines TNF, IL-6, IL-1β, and IFN-γ in response to influenza infection compared to unvaccinated animals." (PMID 40612502, 2025). "Early secretion of Th17 (IL-8, IL-9, IL-17, IL-6) and Th1 cytokines (TNF-α, IL-15, IL-12p70) were detected in severe influenza patients, which were involved in cell-mediated immunity, may be associated with pathogenesis and autoimmune diseases induced by influenza." (PMID 40248710, 2025). "Elevated levels of IL-6 and CXCL8 consistently predict hospitalization and mortality in influenza patients." (PMID 41583233, 2025). "Viral invasion can result in edema and cellular infiltration of the AV node, leading to conduction disturbances, whereas a severe influenza infection leads to a cytokine storm, with elevated levels of tumor necrosis factor (TNF-α), IL-1, and IL-6." (PMID 40585744, 2025). "In the Influenza infection group, the Spring PM exposure induced elevated expression of IFN-γ, IL-1β, IL-6, IL-8, TNF-α, IL-10, MCP-1, and GM-CSF relative to the control exposure." (PMID 40671793, 2025). "We therefore measured the levels of several cytokines, including the pro-inflammatory TNF, IL-1β, IL-6, and IFN-γ, as well as IL-4, IL-10, IL-17A, and IL-22, in BAL samples from mice 5 days after influenza challenge." (PMID 40612502, 2025). "The co-infection of SCoV2/D614G with influenza H5N1 also further upregulated the mRNA expression of IFN-β, IL-6, and MCP-1 compared with the respective single infections." (PMID 40431161, 2025). "After the administration of the influenza vaccine in COPD patients, a direct strong correlation between the level of IL-6 and the frequency of SGCS prescription during BF exacerbations was revealed." (PMID 39937802, 2025). "The group of pregnant women with severe influenza (PSI) exhibited significantly increased levels of IL-4 and IL-6 compared to the PH3 group and an elevated IL-10 level compared to the CN group." (PMID 40558593, 2025). "Studies have shown that patients with severe influenza, particularly those developing ARDS, exhibit significantly higher IL-6 levels compared to those with mild infections." (PMID 40692679, 2025).
influenza (continued). "Children with severe influenza with CRP ≥ 7.57 mg/L, Serum IL-6 ≥ 9.84 pg/ml, Days from onset of Flu symptoms to hospitalization ≤4.5 days, CSF-TP ≥ 194.8 mg/L and FluA had a significantly increased risk of febrile seizures." (PMID 39507495, 2024). "Specifically, IL6, predicted to signal from DTA+_Sftpc+ cells to AT1, basal, goblet, and ciliated cells, was found to be crucial for lung repair after influenza-induced lung injury in mice." (PMID 38472236, 2024). "We next assessed expression levels of various cytokines and chemokines (i.e., IFNB1, IFNL1, IFNL2/3, IFIT1, IFIT3, OAS1, MX1, IL‐6, CXCL10, and IFITM1) which were triggered by influenza and OC43 virus infections alone or together by qPCR." (PMID 38556468, 2024). "During influenza infection, the host’s immune system releases a large amount of cytokines (such as TNF-α, IL-6, and IL-8) and chemokines, among other inflammatory mediators." (PMID 39410114, 2024). "The data indicated that nasal-spraying Bacillus spores significantly decreased IL-6, IL-8, and TNF-α cytokine overreacted production, and to some extend increase nasal IgA level in immunological responses to influenza infection." (PMID 37684332, 2023). "We found that empagliflozin treatment decreased the expression of IL-6, CCL2, and CCL5 in BMDMs and IL-6 and CCL2 in RAW264.7 macrophages during influenza infection." (PMID 38112660, 2023). "Complete or partial blocking was also observed in 2 of 6 anti–IL-6+ samples and in all 3 anti–GM-CSF+ samples, 2 of which were Stanford ICU samples and 1 of which was an influenza sample." (PMID 36752204, 2023). "Empagliflozin treatment decreased the expression of the inflammatory cytokines IL-1β, IL-6, and CCL2; the percentage of inflammatory monocytes and inducible NO synthase–positive macrophages; and IFN response genes Stat1 and CXCL9 during influenza infection." (PMID 38112660, 2023). "The core network, including the pro-inflammatory TNFα, IL-6, IL-1β, MAPK, and RIG-I receptor signaling pathways, is further confirmed as the critical target of TFA anti-influenza efficacy." (PMID 35123452, 2022). "After 14 days of LS intervention, the levels of IL-1ra, Eotaxin, IFN-γ, IL-6, IL-10, IL-13, SCF and TRAIL in serum of participants with influenza infection were significantly decreased compared with Placebo group." (PMID 36034844, 2022). "Next, eight key targets were identified, including TLR4, CD14, MyD88, NF-κB p65, HIF1 α, VEGF, IL17A, and IL6, which were verified to be key targets for HSSD in the treatment of influenza." (PMID 36386710, 2022). "A core network containing the pro-inflammatory TNFα, IL-6, IL-1β, MAPKs, and RIG-I receptor signaling pathway was further confirmed as the crucial targets for anti-influenza efficacy of TFA." (PMID 35123452, 2022). "In the oral cavity, IL-6 is a crucial cytokine involved in the host response against bacterial infection and together with IFN-α, is important in host defense to influenza infection." (PMID 35686128, 2022). "After 14 days of LS intervention, the levels of IL-1ra, IL-6, IL-10, IL-13, Eotaxin, IFN-γ, SCF and TRAIL in serum of participants with influenza infection were significantly decreased compared with Placebo group (p < 0.05 or p < 0.01)." (PMID 36034844, 2022). "With the merger of PPI network, we have identified a core network, including TNF, IL-6, IL-1B, JUN, and MAPK1, as crucial targets of the anti-influenza efficacy of TFA." (PMID 35123452, 2022). "Huoxiang Suling Shuanghua Decoction exerts an anti-influenza effect by affecting the expressions of mRNA and protein including TLR4, CD14, MyD88, NF-kB p65, HIF-1α, VEGF, IL17A, IL6, and inhibiting the accumulation of inflammation." (PMID 36386710, 2022). "During influenza, cytokines and chemokines such as type I and III interferons (IFNs), IL-6, CXCL8, CCL2, CCL3, CCL4, and CCL5 are produced at the site of infection (Wareing and others 2004)." (PMID 35674675, 2022).
influenza (continued). "An experimental study in a severe influenza model in mice showed the high potential of DADA in reducing the cytokine storm including IL-2, IL-6, IFN-α, TNF, and IFN-γ, in addition to its role in restoring the down-regulated PDH activity caused by influenza." (PMID 35355991, 2022). "In critically ill patients with influenza, disease severity is also related to elevated levels of TNF-α, IL-6, IL-8, and IL-10." (PMID 34987205, 2022). "In a mouse model of influenza infection, germinal center TFH were found to be unresponsive to IL-2 through an IL-6 dependent mechanism." (PMID 36420277, 2022). "The analysis using CytoHubba, TNF, IL10, IL-6, IL-1B, JUN, and MAPK1 was found to have the highest average scores and identified as crucial targets for the anti-influenza efficacy of TFA." (PMID 35123452, 2022). "Levels of IL-6, IL-8, TNF-α, and CCL3 were also increased in our cohort of pandemic influenza A(H1N1) patients, validating our previous observations." (PMID 33995342, 2021). "In another study, long-term PM2.5 inhalation lowers the capacity of pulmonary macrophages to secrete IL-6 and IFN-β, a disorder in the pulmonary innate defense system which results in increased death rates following influenza infection." (PMID 33924663, 2021). "In influenza inoculated BMMCs, signaling through double-stranded RNA-sensing PRRs RIG-I and TLR3 strongly induces IL-6 and the proinflammatory leukotriene LTB4." (PMID 33680987, 2021). "Azithromycin and other macrolides, like bafilomycin A1, erythromycin, and clarithromycin were found to impede the making of IL-1β, IL-6, IL-8, TNF-α, and ICAM-1 in influenza- and RV-modeled infections." (PMID 33937285, 2021). "Both IL-6 and NLR have been used as prognostic markers in both, influenza and community-acquired pneumonia." (PMID 33819261, 2021). "In contrast, LCN2 deficiency was associated with increased bronchoalveolar lavage (BAL) levels of proinflammatory cytokines (i.e. IL12, interferon [IFN]γ, IP-10, IL6, MCP-1, BAFF and IFNα) three days after influenza infection." (PMID 33905460, 2021). "It has been shown that influenza upregulates TNF-α, interleukin (IL)-1β, and IL-6 and that these cytokines increase trypsin expression in endothelial cells." (PMID 33562193, 2021). "However, whether there is a post-vaccine increase or not across the board, elevated serum IL-6 is linked to poor antibody responses to influenza vaccination." (PMID 36845567, 2021). "These patients had a sustained production of IL-6 and TNF-α, which was unique when compared to a retrospective cohort of influenza H1N1 2009 patients." (PMID 34728719, 2021). "At the late stage of infection, L. plantarum (O6CC2) decreases IL6 and TNF-α production to control influenza-mediated inflammation." (PMID 33897683, 2021). "Although elevated levels of the cytokine interleukin 6 (IL-6) are often identified as a key correlate, SARS-CoV-2 levels of IL-6 generally fall far short of those noted in influenza cytokine storms." (PMID 33306746, 2020). "RANTES, IL-1β, IL-6, and TNF-α induced by influenza result in pro-inflammatory Th1-type immune responses in the infected host." (PMID 32269562, 2020). "RAW264.7 macrophage cells and primary murine alveolar macrophages also showed increased IL-6, TNF-α, IFN-β, and/or IL-1β production in the presence of 1-methyltryptophan another IDO pharmacological competitive inhibitor, following influenza infection." (PMID 32267860, 2020). "But severe influenza patients with aspergillosis mostly belonged to the H1N1 category and accompanied with higher inflammatory level represented by CRP and IL-6." (PMID 33537328, 2020). "Ox-LDL synergistically increases the expression of pro-inflammatory molecules such as IL-1β, IL-6, TNFα, and MMP-9 in response to H1N1 PDM 2009 influenza in HUVEC cells." (PMID 33193350, 2020).